LAMP1 (lysosome associated membrane protein 1)
Diseases named in the same sentence as LAMP1 in open-access papers (continued):
Sharing a sentence is not in itself a finding about the gene and the disease.
atherosclerosis (2 papers, 2015 to 2025). A disease characterized by the build-up of fatty material and calcium deposition in the arterial wall resulting in partial or complete occlusion of the arterial lumen. "The LAA mechanism clots demonstrated elevated levels of proteins such as CD59, LAMP1, and ELANE, which are associated with the ubiquitin‐proteasome pathway and the progression of atherosclerosis." (PMID 40079446, 2025). "In addition, reduced expression of LAMP-1 has been observed in atherosclerosis." (PMID 25961956, 2015). "Proteins including CD59, LAMP1, and ELAN involved in LAA play crucial roles in the survival, proliferation, and migration of macrophages, potentially influencing the development of atherosclerosis in large arteries." (PMID 40079446, 2025).
cardiac ischemia (2 papers, 2022 to 2024). "In the context of cardiovascular disease, CTRP3 can resist apoptosis and oxidative stress injury, and alleviate myocardial ischemia/reperfusion injury via the LAMP1/JIP2/JNK signaling pathway." (PMID 38278820, 2024). "Interestingly, cilostazol protected against myocardial ischemia by increasing LAMP1 expression." (PMID 35114641, 2022).
Chediak-Higashi syndrome (2 papers, 2020 to 2021). ChC)diak-Higashi syndrome (CHS) is a rare severe genetic disorder generally characterized by partial oculocutaneous albinism (OCA), severe immunodeficiency, mild bleeding, neurological dysfunction and lymphoproliferative disorder. "LAMP1 is associated with Lysosomal Trafficking Regulator (LYST), which causes the multi-system Chediak-Higashi Syndrome." (PMID 33630878, 2021).
CLN5 disease (2 papers, 2020 to 2021). "Intracellular LAMP‐1 expression was generally low in both controls and patients with CLN‐subtypes (CLN1 disease and CLN5 disease) without lymphocyte vacuolization." (PMID 32685355, 2020).
cyst (2 papers, 2022 to 2025). A sac-like closed membranous structure that may be empty or contain fluid or amorphous material. "Significantly, germ cell death is blocked by knockdown of either the endosomal component Rab5 or the lysosomal associated protein Lamp1, within the cyst cells." (PMID 35714186, 2022). "The evidence for cyst cell involvement in germline acidification came from live imaging of Lamp1, a lysosomal membrane protein and an essential component of the phagocytosis machinery." (PMID 41427251, 2025). "Most significantly, components of the cyst cell phagocytic machinery, namely, Rab5, Lamp1, Ced-12, Crq, and Drpr, were required for GCD." (PMID 35714186, 2022). "Live imaging (n = 3) revealed Lamp1-GFP–positive lysosomes within cyst cells incorporating into phagosomes." (PMID 35714186, 2022). "S2A), in Lamp1-GFP flies, Lamp1 localized in a punctate pattern with Armadillo, a cyst cell marker (n = 23; fig." (PMID 35714186, 2022).
epilepsy (2 papers, 2022 to 2024). A brain disorder characterized by episodes of abnormally increased neuronal discharge resulting in transient episodes of sensory or motor neurological dysfunction, or psychic dysfunction. "Epilepsy pericytes, had the lowest number of LAMP-1 positive granules and intensity, while PD pericytes had the highest." (PMID 36243723, 2022).
fibrosis (2 papers, 2023 to 2025). the formation of excess fibrous connective tissue in an organ or tissue in a reparative or reactive process. "Finally, we confirmed our findings in vivo using a fibrosis mouse model, where we found a greater abundance of Lamp1+ cells." (PMID 40545776, 2025).
glaucoma (2 papers, 2023 to 2026). Increased pressure in the eyeball due to obstruction of the outflow of aqueous humor. "Impaired mitophagy has been observed in both rat and mouse models of glaucoma with decreased levels of the lysosome-associated membrane protein 1 (LAMP1) and increased mitophagosome formation, indicating that the mitochondria are not being recycled efficiently by the lysosomes." (PMID 37250427, 2023).
glycogen storage disease (2 papers, 2015 to 2022). "We also compared Lamp1 staining in skeletal muscle from a mouse model for Pompe's Disease, a glycogen storage disease in which the mice present with severe muscle loss and weakness." (PMID 26733885, 2015).
hemorrhagic fever (2 papers, 2021 to 2024). An infectious disease caused by certain viruses or bacteria that can damage the walls of tiny blood vessels, making them leak, and can hamper the blood's ability to clot and cause severe, life-threatening illness. "Instead, it resembles molecules such as NPC1 and LAMP1—so called intracellular receptors for hemorrhagic fever viruses—which promote viral fusion with endolysosomal membranes, but do not mediate virus attachment to cells." (PMID 38359079, 2024).
high-grade gliomas (2 papers, 2016 to 2024). "The expression of LC3-II and LAMP-1 in malignant glioma cells are rescued by si BECN1 following treatment with TGF-β1 (5 ng/ml) for 24 hours." (PMID 26909607, 2016).
kidney transplant (2 papers, 2016 to 2019). A surgical procedure in which one or both kidneys from a donor are implanted into a recipient. "The release of CD107a/Lamp1+ cytotoxic granules, resulting from the recognition of rituximab-coated B cells by NK cells, was analyzed in 148 kidney transplant recipients (KTRs, mean graft duration: 6.2 years)." (PMID 27563301, 2016).
Lassa virus infection (2 papers, 2018 to 2022). "We propose that in this manner, Lamp1 increases the overall efficiency of Lassa virus infection." (PMID 29295909, 2018). "Importantly, whereas abrogation of one molecule (NPC1/Lamp1) completely inhibits EBOV or Lassa virus infection, ASFV infection was only partially inhibited and, in view of our results, could involve the interaction of several endosomal proteins." (PMID 35081156, 2022).
lupus nephritis (2 papers, 2021 to 2025). Glomerulonephritis in the context of systemic lupus erythematosus. "In a proteomic analysis of the urine samples of a large cohort of patients with lupus nephritis, LAMP1 was associated with the severity of inflammatory activity in the kidney biopsy." (PMID 40760840, 2025). "Soluble LAMP1 was increased in the urine and serum of patients with lupus nephritis, and was especially high in patients with proliferative (class III/IV) LN." (PMID 40760840, 2025). "In a comprehensive analysis of neutrophil phenotypes, we identified LAMP1 (CD107a) as a differentially expressed neutrophil marker in patients with lupus nephritis." (PMID 40760840, 2025). "Systemically increased LAMP1 indicates a generalized increase in neutrophil activation in patients with lupus nephritis, likely reflecting processes such as NETosis, which might contribute to LAMP1 release." (PMID 40760840, 2025). "In addition, soluble LAMP1 was increased in the serum and urine of patients with lupus nephritis and correlated with proteinuria and inflammatory activity in the kidney biopsy." (PMID 40760840, 2025). "Specifically, LAMP1 expression was not different between patients with and without LN or between active and inactive lupus nephritis." (PMID 40760840, 2025).
lymph node metastasis (2 papers, 2022 to 2024). "Furthermore, overexpression of LAMP1 correlates with lymph node metastasis in NSCLC." (PMID 39669571, 2024).
myocardial infarct (2 papers, 2022). "In a myocardial infarction (MI) rat model, MSC-ABs were corroborated to activate the lysosomes in endothelial cells (ECs) and increase the protein expression of lysosomal-associated membrane protein 1 (LAMP1) that maintains lysosomal structural integrity and function." (PMID 36497136, 2022). "However, mice injected to LV-CTRP3 could reverse the inhibitory effects of I/R injury on LVEF and LVFS levels and protein levels of CTRP3, LAMP1, JIP2 and p-JNK, and the promotive effects on myocardial infarct volume, apoptosis, and the contents of ROS, MDA and c-Tn1 (P < 0.05)." (PMID 35114641, 2022).
nephrotic syndrome (2 papers, 2014 to 2021). A collection of symptoms that include severe edema, proteinuria, and hypoalbuminemia; it is indicative of renal dysfunction. "In vivo, staining with lysosome-associated membrane protein-1 (LAMP-1) was performed on tissue from a Denys-Drash trangenic mouse model of nephrotic syndrome." (PMID 24924335, 2014). "A Denys-Drash murine model of nephrotic syndrome established to determine if lysosome activity in proteinuric mice demonstrated increased glomerular staining of LAMP-1 as compared to wild type mice." (PMID 33834029, 2021).
Niemann-Pick disease (2 papers, 2020 to 2023). A group of inherited, severe metabolic disorders in which sphingomyelin accumulates in lysosomes in cells. "An animal study with mice found that abnormal LAMP1 glycosylation was potentially associated with Niemann-Pick disease, but none of this kind of studies were found in cancer research." (PMID 36743215, 2023).
pancreatitis (2 papers, 2020). Inflammation of the pancreas. "Decreased pancreatic lysosomal-associated membrane protein 1/2 (LAMP1/2) and lysosomal dysfunction have been reported in human and mouse alcoholic pancreatitis, which may account for the accumulation of large vacuoles in acinar cells in subjects with pancreatitis." (PMID 32349207, 2020). "Moreover, mice with genetic deletion of Atg5, an autophagy-related gene that regulates the formation of autophagosomes, or that of lysosomal-associated membrane protein 1/2 (LAMP1/2), led to the development of spontaneous pancreatitis." (PMID 32349207, 2020).
prion disease (2 papers, 2011 to 2021). A transmissible disease that is caused by a protein that is able to induce abnormal folding of normal cellular proteins, leading to characteristic spongiform brain changes, which are associated with neuronal loss without an inflammatory response. "We wondered whether the association of LAMP1 with vacuoles can also be observed in other model systems of prion disease." (PMID 34291577, 2021).
Renal neoplasm (2 papers, 2018 to 2021). The presence of a neoplasm of the kidney. "Diffuse LAMP1 staining thus has a sensitivity of 91.7% and specificity of 100% to distinguish chRCC from other renal neoplasms." (PMID 34482820, 2021). "We present one of the first differential proteome profiling studies on ROs and chRCCs and highlight differential abundance of LAMP1 and ITGAV in these renal tumors." (PMID 30087584, 2018).
vitiligo (2 papers, 2017). Generalized well circumscribed patches of leukoderma that are generally distributed over symmetric body locations and is due to autoimmune destruction of melanocytes. "In particular, thyroid tissues from HT patients without vitiligo, and normal thyroid tissues, were both negative for the expression of NKI/beteb, Pmel17, TRP-1, HMB-45, and S100, whereas they were positive for the expression of TRP-2, lysosome-associated membrane protein 1 (LAMP1), and CD69." (PMID 29163360, 2017).
acute pancreatitis (1 paper, 2022). An acute inflammatory process that leads to necrosis of the pancreatic parenchyma. "Depletion of LAMP1 and LAMP2 during acute pancreatitis was reported and suggested as the mechanism responsible for the disruption of the autophagic flux, vacuolisation, and progression of acute pancreatitis." (PMID 36010591, 2022).
adenoma (1 paper, 2020). A neoplasm arising from the epithelium. "The gene coding for LAMP1 is located on chromosome 13q, gain of which is one of the seven CAEs used for classifying adenomas as high‐risk." (PMID 31784980, 2020). "Next to Hp, LAMP1, SYNE2, and ANXA6 were selected in the analysis for high‐risk adenomas, and also LRG1, RBP4, and FN1 for the high‐risk adenomas and CRCs." (PMID 31784980, 2020). "A protein panel, consisting of haptoglobin (Hp), LAMP1, SYNE2, and ANXA6, was identified for the detection of high‐risk adenomas (sensitivity of 53% at specificity of 95%)." (PMID 31784980, 2020). "We identified a biomarker panel of Hp, LAMP1, SYNE2, and ANXA6 for identification of high‐risk adenomas and two biomarker panels – Hp and LRG1, as well as Hp, LRG1, RBP4, and FN1 – for identification of high‐risk adenomas and CRCs that outperformed hemoglobin." (PMID 31784980, 2020). "We conclude that Hp, LAMP1, SYNE2, LRG1, RBP4, FN1, and ANXA6 may be of value as stool biomarkers for early detection of high‐risk adenomas and CRCs." (PMID 31784980, 2020).
alcoholic liver diseases (1 paper, 2021). A disorder caused by damage to the liver parenchyma due to alcohol consumption. "In alcoholic liver disease, alcohol decreases lysosomal function in hepatocytes and macrophages, and expression of lysosome-associated membrane protein 1 (LAMP1) and LAMP2 is downregulated." (PMID 34368234, 2021).
alcoholic pancreatitis (1 paper, 2020). Acute or chronic inflammation of the pancreas due to excessive alcohol drinking. "Immunofluorescence staining showed punctate LAMP1 staining in acinar cells in both normal and alcoholic pancreatitis samples, but the number of LAMP1 puncta decreased significantly in alcoholic pancreatitis pancreas." (PMID 31987928, 2020). "In line with our findings in mice, decreased LAMP1 and TFEB nuclear staining were also observed in human alcoholic pancreatitis tissues." (PMID 31987928, 2020). "Furthermore, immunoblotting analysis also revealed decreased levels of pancreatic LAMP1 and LAMP2 proteins in alcoholic pancreatitis patients compared with normal healthy control donors." (PMID 31987928, 2020).
Anxiety (1 paper, 2021). Intense feelings of nervousness, tension, or panic often arise in response to interpersonal stresses. "To confirm the involvement of lysosomal exocytosis in zebrafish behavior, we exposed WT zebrafish to alarm substances, which is known to evoke an anxiety behavior and suppress bold behaviors, and evaluated the levels of the Lamp1 protein in the brain." (PMID 34188220, 2021).
atopic asthma (1 paper, 2015). An asthma that is characterized by symptoms that are triggered by an allergic reaction caused by inhaled allergens such as dust mite allergen, pet dander, pollen and mold. "Among the genes identified in the present study (M6PR, TPP1, GLB1, NEU1, ACP2, LAMP1 and HGSNAT) that were significantly associated with lysosomal function, only TPP1 has been confirmed as being associated with atopic asthma." (PMID 25633562, 2015).
Atrophy (1 paper, 2022). Any weakening or degeneration, especially through lack of use. "Mitophagy dysregulation has been denoted as a pathogenic mechanism in muscle atrophy by an increase in LC3-II, p62, and lysosome-associated membrane protein 1 (LAMP1) expression in sarcopenic mice." (PMID 35955849, 2022).
autism (1 paper, 2023). Persistent deficits in social interaction and communication and interaction as well as a markedly restricted repertoire of activity and interest as well as repetitive patterns of behavior. "We analyzed the correlation between LAMP1 gene expressions in cerebella and Autism Diagnostic Interview-Revised (ADI-R) total or ADI-R domain scores based on dataset GSE38322." (PMID 37640746, 2023). "The blood sample expression of LAMP1 was correlated using CARS (Childhood autism rating scale) and ABC (Autism Behavior Checklist) scores." (PMID 37640746, 2023). "Further, in several animal models of autism, Lamp1 expression was found to be significantly upregulated in brain tissues or neurons." (PMID 37640746, 2023). "More notably, LAMP1 also interact with ITGAL, FYN and FERMT3 which were dysregulated in our blood biomarker screening results, suggesting that these proteins involved in focal adhesion and immune regulation may play a vital role in autism." (PMID 37640746, 2023). "LAMP1 protein expression was found to be significantly related to total ABC scores (r = 0.681, P.Value = 0.0435), but not to Childhood Autism Rating Scale (CARS) scores (r = 0.449, P.Value = 0.372)." (PMID 37640746, 2023).
autoimmune thyroid (1 paper, 2017). "Expression of LAMP1 and CD69 in thyroid tissues of AITD patients was upregulated significantly, compared to normal thyroid tissues, while TYR was positively stained only in autoimmune thyroid tissues." (PMID 29362715, 2017).
breast adenocarcinoma (1 paper, 2025). "While all tested cell lines exhibited robust LAMP1 expression by flow cytometry, we selected MDA-MB-231 (breast adenocarcinoma) and Caco-2 (colon adenocarcinoma) as our primary models for subsequent experiments based on their superior expression profiles and experimental tractability." (PMID 40872517, 2025).
candidiasis (1 paper, 2021). Infection with the organism Candida. "Interestingly, we showed that genetic variation in close vicinity of the phagocytosis/phagosome maturation-associated genes ASGR2, LAMP1, RAB42, GEM, ATP6V1B2, and RAB20 are associated with susceptibility to candidiasis." (PMID 33510868, 2021).
cervical (1 paper, 2023). "To confirm the differences in γδ T-mediated cytotoxicity induced by γδ T cells against healthy and HPV+ and cancer-derived cervical organoids, we determined degranulation/Lamp-1 mobilization of γδ T cells by flow cytometry." (PMID 38090581, 2023).
cervical adenocarcinoma (1 paper, 2014). An adenocarcinoma arising from the cervical epithelium. "In the widely used human cell line from cervical adenocarcinoma HeLa, CINCCKVL-chimeric proteins showed substantial co-localization with LTR (GFP-8/LTR co-localization rate: 62.6±2.5%) and tRFP-T-8 localized inside Lamp-1-GFP-positive vesicles which became dilated when treated with cloroquine." (PMID 25207810, 2014).
cholestasis (1 paper, 2022). Impairment of the bile flow caused by obstruction within the liver, or outside the liver in the bile duct system. "First, to verify and further define cholestasis-dependent changes in autophagy proteins in our PSC samples, expression of p62, Beclin1, LC3a/b, ATG5/12, ATG7, LAMP1 and LAMP2 was evaluated by Western blotting using lysates prepared from PSC liver tissue." (PMID 36378690, 2022).
colitis (1 paper, 2025). Inflammation of the colon. "Flow cytometry was performed on brain single cell suspensions to further characterize activated microglia during acute colitis using several markers, including CD45, CD11b, P2RY12, CD11c, CD68, CX3CR1, and LAMP1." (PMID 40457749, 2025).
colon adenocarcinoma (1 paper, 2025). "This study presents compelling evidence that LAMP1 is a promising imaging biomarker for the non-invasive detection of epithelial cancers such as breast and colon adenocarcinomas." (PMID 40872517, 2025). "Biodistribution studies were conducted seven days post-injection in mice bearing breast and colon adenocarcinoma xenografts to evaluate the in vivo pharmacokinetics of 89Zr-DFO-anti-LAMP1 and the IgG control tracer." (PMID 40872517, 2025). "In this study, for the first time, we developed a novel 89Zr-DFO-mAb PET tracer targeting LAMP-1 and demonstrated its potential as an imaging biomarker for the non-invasive detection of breast and colon adenocarcinomas." (PMID 40872517, 2025). "We present evidence indicating that LAMP1 serves as a promising biomarker for the non-invasive detection of breast and colon adenocarcinomas." (PMID 40872517, 2025). "This study aimed to develop a LAMP1-targeted antibody-based PET tracer and assess its efficacy in mouse models of human breast and colon adenocarcinoma." (PMID 40872517, 2025).
cystinosis (1 paper, 2015). Cystinosis is a metabolic disease characterized by an accumulation of cystine inside the lysosomes, causing damage in different organs and tissues, particularly in the kidneys and eyes. "In cystinosis ciPTEC, average size of the individual LAMP1-positive vesicles was enlarged by 35% (p<0.01), and the vesicles demonstrated a different distribution pattern than in the ciPTEC from a healthy donor." (PMID 25811383, 2015).
Danon disease (1 paper, 2021). A lysosomal glycogen storage disease characterized by severe cardiomyopathy and variable degrees of muscle weakness, frequently associated with intellectual deficit. "While dysregulated LAMP1 expression does not cause apparent lysosomal defects, LAMP2 deficiency impairs lysosomal degradation and autophagy and is implicated in Danon disease." (PMID 34445748, 2021).